XIST (X inactive specific transcript)
Diseases named in the same sentence as XIST in open-access papers (continued):
Sharing a sentence is not in itself a finding about the gene and the disease.
tumor (continued). "For example, XIST has been characterized as a tumor suppressor in prostate cancer, but it functions as a ceRNA in bladder cancer and increases AR signaling, an important pathway in tumor development and drug resistance." (PMID 36902032, 2023). "An analysis of published sequencing data on cancer tissues revealed that XIST was activated and expressed in various male tumours characteristics of XCI." (PMID 38148658, 2023). "XIST directly binds and suppresses let-7a-2-3p, a member of the let-7 family of miRNAs with tumor suppressor functions, leading to markedly elevated IL-6 production in ALDH- BC cells (BCCs) and, to a lesser extent, in ALDH+ CSCs." (PMID 36922677, 2023). "On further analysis, XIST was downregulated in tumour tissues, which in females was higher than in males." (PMID 38148658, 2023). "Some researchers have explicitly proposed that XIST is involved in carcinogenesis and tumour suppressor pathways in tumour pathology." (PMID 38148658, 2023). "We provide evidence for the regulation of NME1, a tumour suppressor, through miR‐210/XIST‐mediated epigenetic mechanism." (PMID 36116139, 2022). "Recent studies have confirmed that lncRNA XIST acts as an oncogene accelerating tumor growth in NSCLC." (PMID 35453680, 2022). "In breast cancer, a variety of non-coding RNAs have been found to work as tumor suppressors or tumor-promoting effectors, such as XIST, HOTAIR, GAS5, MALAT1, etc.." (PMID 36230738, 2022). "We therefore tried to separate these effects, starting by testing for non-tumor patient characteristics like age and sex: higher XIST expression was observed in females, and higher RPS4Y1 expression in males." (PMID 35158950, 2022). "The analysis of cancer stemness revealed that XIST was significantly correlated across five tumour types, with a significant positive correlation in KIPAN, PRAD, and TGCT and a significant negative correlation in CESC and BRCA." (PMID 36038831, 2022). "A very recent study explored the clinical value of exosomal XIST secreted in the serum by tumor cells to predict recurrence in patients with TNBC." (PMID 35076579, 2022). "We profiled PMIS‐miR‐210 transduced and untreated CRC cells and tumours for gene expression changes and focused on two genes XIST and NME1 that were significantly affected by miR‐210 inhibition." (PMID 36116139, 2022). "We analyzed the associations among nine lncRNAs (NEAT1, XIST, NORAD, MALAT1, MIR29B2CHG, LINC00943, AC005332.4, AC092718.4, and LINC01146), risk score, tumor purity, and immune cell infiltration." (PMID 35756601, 2022). "The results of RT-qPCR showed that XIST knockdown reduced the level of XIST and enhanced miR-320d abundance in tumor tissues." (PMID 35899235, 2022). "Through in vivo and in vitro experiments, we found that the overexpression of XIST improved the invasion and proliferation of PCa cell lines, whereas knockdown inhibited tumour cells from acquiring these abilities." (PMID 36038831, 2022). "After transfection with XIST-shRNA1, the level of XIST expression in tumour tissues was significantly reduced." (PMID 36038831, 2022). "The importance of XIST in CRC progression is demonstrated by increased levels of XIST in CRCs and its effect on the Wnt/β-catenin signaling pathway, which promotes elevated c-Myc levels and tumor growth." (PMID 35922756, 2022). "Numerous studies have reported that lncRNA-XIST is upregulated in PC tissues and cell lines, and high XIST expression in PC is related to poorer prognosis (larger tumor size, perineural invasion, lymph node micrometastases, and shorter OS)." (PMID 35565245, 2022). "Reportedly, miR-455-3p experiences high expression in OSCC patients, and its overexpression can reverse the anti-tumor effects of X inactive specific transcript (XIST) in OSCC." (PMID 35258410, 2022). "Recently, it was observed that XIST plays critical roles in tumor growth and gene expression control, also thanks to its ability to act as a miRNA sponge." (PMID 35076579, 2022).
tumor (continued). "We demonstrate that the long non‐coding transcript XIST is regulated by miR‐210 correlating with decreased XIST expression in CRC tumours." (PMID 36116139, 2022). "Adenovirus-mediated overexpression of tumour suppressor lncRNA XIST suppressed cellular proliferation and metastasis in PCa both in vitro and in vivo through sponging miR-23a to regulate RKIP expression." (PMID 35159022, 2022). "While we also found SAF-A depletion fully released XIST RNA in this particular mouse tumor cell line, our prior study focused on XIST RNA showed different results and greater biological complexity in other cell lines, including normal primary somatic cells." (PMID 34859278, 2022). "These in vivo experimental results confirmed that BMSCs derived exosomes XIST can promote tumor growth and metastasis by binding miR-655." (PMID 36309693, 2022). "At present, there are few studies on the role of XIST in cardiovascular diseases, mostly tumor related studies." (PMID 35346191, 2022). "Overexpression of XIST suppressed cell proliferation, metastasis and tumour growth both in vitro and in vivo." (PMID 35159022, 2022). "The xenograft model revealed that XIST overexpression greatly reduced the weight and volume of tumors, resulting in smaller tumor sizes." (PMID 35723009, 2022). "Using tumor xenografts in nude mice, it was shown that the XIST/miR-124/EZH2 axis increased tumor growth in vivo in laryngeal squamous cell carcinoma." (PMID 36362406, 2022). "XIST gene expression level was positively correlated with the invasion and proliferation of tumour cells." (PMID 36038831, 2022). "The greatest change in expression of an individual lncRNA was observed for XIST in the case of G114 tumor; however, its level in the parental tumor was extremely low in comparison to HB (control)." (PMID 33245508, 2022). "Our in vivo data suggested that compared to the Con group, suppressed tumor growth occurred in the XIST KO group." (PMID 34295808, 2021). "In order to find the mechanism by which XIST regulates AR protein expression, a relation between miR-124 and XIST was observed; miR-124 has recently been confirmed as a tumor suppressor regulating proliferation, migration, and invasion in many cancers." (PMID 33919565, 2021). "Specifically, XIST serves as a tumor-promoting lncRNA or tumor suppressor in various human malignancies." (PMID 33942699, 2021). "The clustered regularly interspaced short palindromic repeats (CRISPR)/CRISPR-associated protein 9 (CRISPR/Cas9) system validated the role of XIST knockout in tumor development in vivo." (PMID 34295808, 2021). "All these events are initiated when XIST (X-inactive-specific transcript) expression is decreased in BC that activates MSN-c-Met which increases tumor cell stemness." (PMID 33522932, 2021). "Recently, one research article provided evidence of a relationship between XIST and the inhibition of tumor progression in vitro." (PMID 34640640, 2021). "Mice that received the treatment and were, therefore, rid of all tumor cells with reduced XIST expression showed significantly delayed BCBM onset and a significantly slower BCBM growth rate." (PMID 34439289, 2021). "Ablation of XIST in tumour cells also triggers microRNA‐503 secretion in EVs, whose internalization by microglia cells induces M1‐M2 polarization and turns up levels of immunosuppressive cytokines." (PMID 33145869, 2021). "X chromosomal inactivating gene (XIST) is a lncRNA that has been shown to play a role in promoting or preventing cancer in different types of tumor disease." (PMID 33858324, 2021). "Studies regarding the role of XIST in OC are also contradictory–some claim upregulation of XIST leads to stimulation and increased proliferation of OC cells, while others claim it suppresses OC proliferation and tumor growth." (PMID 34680193, 2021). "In HO-8910 xenografts, tumor weight and volume were reduced by sh-XIST or miR-149-3p mimic; impacts of sh-XIST on tumor weight and volume were abrogated by miR-149-3p inhibitor." (PMID 33542185, 2021).
tumor (continued). "Xist is a well-known lncRNA derived from XIST gene which can regulate X-chromosome inactivation, and recognized as a tumor promoter in various malignant tumors." (PMID 33777808, 2021). "Knockdown of XIST reversed the anti-tumor effect exerted by PXN, which highlighted the therapeutic role in GC." (PMID 34930117, 2021). "Recently, targeting the XIST/miR-335 axis was shown to elevate the anti-tumor effects of platycodin D in BCs, thus suggesting a therapeutic strategy for BCs." (PMID 34930117, 2021). "lncRNA XIST act as an oncogene by promoting tumor growth and EMT in several cancer types such as colorectal cancer and retinoblastoma where it is demonstrated to be a marker of poor prognosis." (PMID 33522932, 2021). "In our review, we collected and analyzed the recent studies on the impact of XIST in human tumor development." (PMID 34930117, 2021). "According to a series of recent reports, XIST is down-regulated in HCC thus serves as a tumor suppressor via inhibiting oncogenic miR-497 via the competing endogenous RNA mechanism." (PMID 34285143, 2021). "XIST silencing suppresses autophagy, tumour proliferation, and enhances apoptosis, additionally sensitizing RB cells to vincristine, the efficacy of which is often limited because of chemoresistance." (PMID 33803216, 2021). "In CRC, Previous studies have indicated that METTL14 suppressed the tumor progression by regulating miR-375, lncRNA XIST and SOX4, respectively." (PMID 34916487, 2021). "For instance, XIST and SBF2-AS1 can the induce M2 polarization of tumor-associated macrophages, which are indispensable cells within the tumor immune microenvironment." (PMID 34885209, 2021). "The great weight coefficient given by these gender-related lncRNAs were obvious in small size tumor (G1/G2 < 5 cm), and was rapidly lost when the tumor became malignant (G3/G4, > 5 cm) and the expression of XIST and FTX were significant inhibited." (PMID 34557343, 2021). "XIST has been shown to be abnormally overexpressed in multiple cancers, exhibiting the properties of an oncogene in promoting tumor growth, invasion, metastasis, colony formation, and chemotherapy resistance." (PMID 34930117, 2021). "In vivo research also uncovered that XIST knockdown impeded tumor growth and prolonged the survival of nude mice." (PMID 33501488, 2021). "Consistently, MET expression was positively correlated with XIST but negatively with miR-34a levels in tumor specimens." (PMID 33763422, 2021). "XIST knockout in the mammary glands of mice was significantly promoting the primary tumor growth and metastasis in the brain." (PMID 33522932, 2021). "It has been reported that XIST increases tumor cells proliferation and suppresses apoptosis in DOX-treated MDA-MB-231 cells through upregulation of the anillin actin-binding protein (ANLN)." (PMID 34425750, 2021). "LncRNA XIST was downregulated in GBM, and overexpression of XIST resulted in inhibited progression of GBM through the upregulation of tumor suppressive miR‐152." (PMID 33942556, 2021). "It has been suggested that the deregulation of XIST plays an important role in tumor progression and prognosis." (PMID 34425750, 2021). "XIST is involved in multiple aspects of carcinogenesis, including tumor onset, progression, and prognosis." (PMID 34930117, 2021). "Inhibition of JPX/FTX transmits the signal to XIST, decreasing its expression levels and completing the sequence that ultimately leads to both activation of tumor growth and stimulation of metastatic capacity." (PMID 33053887, 2020). "Accumulating evidence shows that XIST functions as an oncogene accelerating tumor progression and metastasis in various cancers." (PMID 32489472, 2020). "Treatment with silencing XIST decreased tumor volume and weight, while overexpression of MYC reversed the trends (p < 0.05)." (PMID 33228517, 2020). "Knocking out XIST significantly promoted apoptosis and inhibited the proliferation, migration and invasion of tumor cells." (PMID 32489472, 2020).
tumor (continued). "It has been extensively acknowledged that lncRNA–miRNA–mRNA interactions assume an essential part in tumor occurrence, and previous studies have indicated that XIST plays an important role in cancers mainly by interacting with diverse miRNAs." (PMID 33364236, 2020). "A panel of in vitro and in vivo studies confirmed that XIST knockdown restricted tumour cell growth, invasion and EMT." (PMID 32779318, 2020). "We found that XIST levels were more elevated in the tumours of patients who had received DDP treatment, compared to patients not treated with DDP." (PMID 32209729, 2020). "We found that the tumor size and number were smaller in the mice injected with stable XIST knockdown SNK-6 cells." (PMID 33364236, 2020). "Consistent with previous studies, we also found that miR-497 suppressed the XIST-induced ENKL tumor growth and metastasis, which is an important target in patients with high XIST expression." (PMID 33364236, 2020). "XIST appears to be both tumor-promoting and tumor-suppressive, depending on cancer type and context." (PMID 32295632, 2020). "In LSCC, the lncRNA X-Inactive Specific Transcript (XIST) promotes the tumor progression by sequestering miR‐144 to regulate IRS1 expression." (PMID 33046994, 2020). "High expression of XIST was found in patients with larger tumor diameters, and advanced TNM stages (III and IV)." (PMID 32760219, 2020). "LncRNAs can function either as oncogenes (e.g., HOTAIR, MALAT1, H19) or as tumor suppressors (e.g., HOTAIRM1, NKILA, XIST) by targeting genes that foster or prevent tumor development and progression, respectively." (PMID 33049922, 2020). "It is reported that XIST expression is correlated with tumor size, N1, M1, and III+IV stages of CRC, and it can be an independent prognostic biomarker for CRC patients." (PMID 32280704, 2020). "In OS cells in vitro and in vivo, targeting XIST inhibited cancer cell proliferation and invasion and suppressed subcutaneous tumor growth in mice." (PMID 31189404, 2019). "It indicated that miR-141-3p is down-regulated in tumor tissues, while XIST is highly expressed in PC." (PMID 31213574, 2019). "Secondly, considering activated microglia can modulate neurodegenerative diseases and tumor progression under pathological conditions, they also investigated the role of XIST in microglia." (PMID 31744046, 2019). "In vivo studies also validated knocking out XIST gene suppressed tumor growth and improved survival in NICD mice." (PMID 31213574, 2019). "Our results revealed the regulatory network among XIST, P65 and PUMA in OS cells, and confirmed the key role of PUMA in XIST downregulation-induced anti-tumor effect." (PMID 31189404, 2019). "Overall, our findings indicate that lncRNA XIST can regulate HCC tumor growth through the miR-497-5p-PDCD4 axis." (PMID 31384173, 2019). "Considering all 250 TGCT tumor samples, they showed a significantly lower relative amount of methylated XIST fragment as compared to testicular parenchyma samples (p < 0.0001)." (PMID 31533343, 2019). "We found that miR-141-3p has a lower level expression in tumor tissues while XIST is highly expressed in tumor tissues, XIST is negatively correlated with miR-141-5p." (PMID 31213574, 2019). "High expression of X-inactive specific transcript (XIST) was shown to correlate with larger tumor size and higher tumor/node/metastasis (TNM) stage." (PMID 30813594, 2019). "Knockdown XIST inhibits tumor growth by suppression of cell migration, invasion and as well as proliferation." (PMID 31213574, 2019). "Subsequent works have demonstrated quite convincingly the existence of X chromosome gains in TGCTs, both SE and NS alike, and XIST expression in both tumor types." (PMID 31533343, 2019). "Then, to evaluate the relationship between lncRNA XIST and miR-497-5p, several mechanistic experiments, including qRT-PCR, Western blotting, transwell assays and tumor xenograft assays, were performed." (PMID 31384173, 2019).